FANCA (FA complementation group A)
Diseases named in the same sentence as FANCA in open-access papers (continued):
Sharing a sentence is not in itself a finding about the gene and the disease.
triple-negative breast carcinoma (1 paper, 2025). An invasive breast carcinoma which is negative for expression of estrogen receptor (ER), progesterone receptor (PR), and human epidermal growth factor receptor 2 (HER2). "To validate the synthetic lethality of FANCA deficiency with PARPi in human cancer models, we generated FANCA-knockout subclones of the triple-negative breast cancer (TNBC) cell lines MDA-MB-231 and BT-549 using CRISPR/Cas9." (PMID 40630542, 2025).
Uterine leiomyoma (1 paper, 2020). The presence of a leiomyoma of the uterus. "We identified that rs2239359 polymorphism, which causes a missense mutation in FANCA, is associated with the rate of proliferation in uterine leiomyomas." (PMID 33202820, 2020). "Taken together, the results in the current study suggested that a FANCA missense mutation may play an important regulatory role in the proliferation of uterine leiomyoma and thus may serve as a prognostic marker." (PMID 33202820, 2020). "Direct sequencing revealed a yet unidentified role of FANCA, a caretaker in the DNA damage-response pathway, as a possible biomarker molecule for the prediction of uterine leiomyoma proliferation." (PMID 33202820, 2020). "Of the numerous clinical manifestations that are related to FANCA mutations, genetic association of FANCA mutations with uterine leiomyoma, especially in relation to the proliferation rate, has not been reported." (PMID 33202820, 2020).
vitiligo (1 paper, 2024). Generalized well circumscribed patches of leukoderma that are generally distributed over symmetric body locations and is due to autoimmune destruction of melanocytes. "rs9926296 (intron variant of FANCA and involved in vitiligo) is found to be depleted only in EAS." (PMID 39060965, 2024).
ZIKV infection (1 paper, 2017). "The 29th exon of FANCA was skipped after ZIKV infection, while one of FANCA’s isoforms (id: TCONS_00119591) was downregulated about 2-fold after ZIKV infection." (PMID 29116029, 2017).
cancer (83 papers, 2005 to 2026). A tumor composed of atypical neoplastic, often pleomorphic cells that invade other tissues. "Collectively, these findings establish FANCA deficiency as a potent determinant of PARPi sensitivity across in vitro and in vivo human isogenic cancer models." (PMID 40630542, 2025). "Our screen identified FANCA deficiency as a driver of PARPi SL that was validated across diverse human cancer models." (PMID 40630542, 2025). "Based on its secondary validation and high prevalence in human cancers, we prioritized FANCA deficiency for further investigation of PARPi synthetic lethality." (PMID 40630542, 2025). "The FANCA gene is involved in an autosomal recessive bone marrow syndrome which causes cancer predisposition in homozygote patients." (PMID 38700789, 2024). "FANCA (FA complementation group A) is associated with tissue proliferation and was found to be overexpressed in many types of cancers." (PMID 35800363, 2022). "WGS data from the Pan-Cancer Analysis of Whole Genomes (PCAWG) dataset of 2,658 whole-cancer genomes across 38 tumour types found the most mutated DNA break repair mechanisms (DBRMs) genes to be FANCA, POLE, PRKDC and RAD51B." (PMID 36289474, 2022). "To explore the significance of this interface in FA and cancer, we mutated five residues of FANCA observed in FA-patients or cancer cells, and examined binding between FANCA CTD and FANCG using yeast two-hybrid analyses." (PMID 32002546, 2020). "Evidence indicates that polymorphisms or mutations in the FANCA gene are related to cancer survival and susceptibility." (PMID 33202820, 2020). "The integrated analysis identified the top 30 significant genes (P<0.01), which comprised genes associated with cancer, whereas the protein-protein interaction analysis indicated a strong association between FANCA and BRCA1." (PMID 23483937, 2013). "Nevertheless, FANCA remains an attractive candidate as either a cancer predisposition gene or a target of genetic or epigenetic inactivation in sporadic tumours." (PMID 15860134, 2005). "The most striking difference was observed in FANCA-mutated cancer cell lines." (PMID 40111122, 2025). "More studies are needed to establish risk of cancer for FANCA heterozygote carriers." (PMID 38700789, 2024). "Similarly, association with increased cancer susceptibility has been associated with germline variants of FANCA, FANCM, and FANCR (RAD51), among others." (PMID 38023254, 2023). "Higher percentages of altered FANC genes have been found in HNSCC patients unaffected by FA, as well as in various cancer types, both sporadic and hereditary: among them, breast and ovarian cancer with mutations occurring most likely in FANCA, FANCS/BRCA1, and FANCD2/BRCA2 genes." (PMID 35954197, 2022). "However, the structure of FANCA coupled with future experimental data on a wider range of FANCA mutants should shed light on FA- and cancer-associated mutations." (PMID 32002546, 2020). "Loss of FANCA, a gene involved in homologous recombination, may also sensitise this cancer to PARP inhibition." (PMID 32392735, 2020). "Both SMARCA2 and SMARCA4 are tumor suppressors and mutations are frequently found in cancers, which may suggest an additional link between FANCA mutations and cancer predisposition." (PMID 31461451, 2019). "Coincidently, deficiency in FANCA also results in inflammation and cancers." (PMID 24349332, 2013). "In support of this hypothesis, deficiency in FEN1 causes partially similar phenotypes as FANCA, i.e. inflammation and cancers." (PMID 24349332, 2013). "As FANCA is likely to function as a tumour suppressor, it is plausible that allelic variants with altered activity may modify cancer risk." (PMID 15860134, 2005). "FANCA gene mutation might be a predisposition to the development of a second primary cancer." (PMID 32850347, 2020). "Our study establishes FANCA genetic alterations in cancer as a promising selection criterion for PARP1 inhibitor treatment." (PMID 40630542, 2025).
cancer (continued). "Here, we report 9 out of 24 patients with non-contributory family history, harboring germline heterozygous deleterious mutation in well-known cancer predisposing genes (CHEK2, RAD51C, BRCA2, FANCA, RET, FH, and BAP1)." (PMID 38700789, 2024). "All five genes (BAP1, FANCA, RET, FH, and RAD51C) are well-known cancer predisposing genes with incomplete penetrance and variability of expression." (PMID 38700789, 2024). "The strong role for FAAP20 in HR and cell proliferation compared to FANCA elucidates repair mechanisms that can be preferentially utilized by dividing cancer cells." (PMID 37620397, 2023). "Eight patients harbored monoallelic variants in high/moderate penetrance cancer genes associated with autosomal dominant inheritance and a second variant in a gene associated with a recessive disorder (MUTYH, FANCA, NTHL1) or low penetrance cancer (TYR)." (PMID 36132150, 2022). "In our cohort, fourteen patients harbored a monoallelic P/LPV associated with recessive disorders (NTHL1, RECQL4, ERCC3, FANCA, and BLM) and one patient harbored PV in a low penetrance cancer gene (TYR)." (PMID 36132150, 2022). "Core (BRCA1/2, PALB2), and any HRR mutations (BRCA1/2, PALB2, CHEK2, FANCA, ATM) occurred in 13 (10.3%) and 22 (17.5%) cancers, respectively." (PMID 36124727, 2022). "Overall, the six genes that had PVs with prevalences greater than one percent for any patient cohort (ATM, BRCA1, BRCA2, CHEK2, CDKN2A and FANCA) comprise a heterogenous group of genes that reflect the complexity of this cancer." (PMID 34255164, 2021). "To date, 22 FA genes have been identified (FANCA to FANCW), with mutations in any one of these genes leading to bone marrow failure, developmental abnormalities, and a predisposition to cancer." (PMID 34830134, 2021). "Simple somatic mutation (SSM) frequency of FA genes in the cancer population shows a rather even distribution among FA genes, with modest elevation in the ID2 complex, FANCA and FANCM of the core complex, and some downstream HR components." (PMID 32190289, 2020). "Six pathogenic variants (in BRCA1,BMPR1A,FANCA,FANCC,NBN genes) with cancer related phenotype and three unsolicited variants (in BRCA2,PALB2,RAD50 genes) were reported to patients." (PMID 31937788, 2020). "Responses to PARP inhibition have been seen in patients with FANCA alterations and preclinical data suggest that PTEN loss sensitises cancers to PARP inhibitors, with reported cases of exceptional responses to olaparib." (PMID 32392735, 2020). "FANCA is able to promote error-prone repair pathways such as SSA that permit cancer-driving genomic instability." (PMID 28239445, 2017). "Analysis of individual cancer types revealed significant early onset for germline truncations of FANCA in HNSC, BRIP1 in LUSC and ATM in STAD." (PMID 26689913, 2015). "Of those listed, ERCC3, FANCA and FANCM LoF variants are good candidates for further research as potential cancer-susceptibility mutations as the normal functions of their gene products are in DNA repair pathways." (PMID 26023681, 2015).
cancer (continued). "Although the study indicated that the risk of cancer was not increased among all FA heterozygotes, only two genes were conclusively excluded as potential risk genes, namely FANCA and FANCC (observed versus expected ratios (O/E) of 0.92 and 0.91, respectively)." (PMID 38814507, 2024). "Consistent with the literature, the most frequently mutated gene was FANCA; however, other genes were unexpectedly prominent, such as FANCP and FANCJ, which may be due to somatic mutations in cancer samples that are ambiguously labeled on ClinVar submissions." (PMID 35955545, 2022). "We have used CRISPR/Cas9 editing tools in order to interrupt the human FANCA gene by the generation of insertions/deletions (indels) in exon 4 in two cancer cell lines from sporadic HNSCC having no mutation in FA-genes: CAL27 and CAL33 cells." (PMID 33918752, 2021). "However, the current data on increased susceptibility to cancer in FANCA heterozygote carriers is conflicting and not supportive of a strong effect." (PMID 38700789, 2024). "Among the interface genes in the Her2+_TNBC module, the known cancer-related genes are mostly DNA repair genes, such as BARD1, BRIP1, BRCA1, BRCA2, FANCA, FANCC, FANCD2, and FEN1." (PMID 35992864, 2022). "At the genetic level, tumor mutation burden and alterations in DNA damage response and repair genes including ATM, ERCC2, BRAC-2, FANCA, MSH6, and POLE can to some extent predict the response of ICIs in specific cancer types." (PMID 33791296, 2021). "Alongside FA-mediated drug resistance are observations that FANCA and FANCT/UBE2T correlate with poor prognosis and survival of cancer patients." (PMID 32190289, 2020). "FANCA was overexpressed in six databases other than LU, and POLD1 was highly expressed in in cancer tissues in six databases other than HENDRIX." (PMID 32762026, 2020). "A literature and COSMIC search revealed that several of these mutations have been detected in other model systems and other cancer subtypes, e.g. PARP-1 (V377S), ATR (K297 N), FANCA (G809 N), and MLH3 (I541V)." (PMID 30305041, 2018). "Markedly, the CTA genes ATAD2, CEP55, FANCA, KIF2C, NUF2, OIP5, and PBK had significantly positive expression correlations with the PLK1 expression in 30 cancer types (Pearson correlation, FDR<0.1)." (PMID 30631355, 2018). "Here, we found that repression of FANCA and FANCD2 resulted in a significant elevated effect with the LysoTracker dye retention suggesting lysosomal health also depends on FA gene function in non-cancer cells." (PMID 41188232, 2025). "Deletions in the FANCA, POLD1, and STK11 genes were observed in cancer patients only." (PMID 33431054, 2021). "For the cancer phenotypes, the reverse genetics models were enriched in DNA repair functions (p = 2×10−5, FDR p = 0.03) (POLG/FANCI, SLX4/FANCP, XRCC1, BRCA1, FANCA, CHD1L) while the additive model showed enrichment related to chromatid segregation (p = 4×10−6, FDR p = 0.005) (KIF25, PINX1)." (PMID 24349080, 2013). "And the lack of FANCA and FANCG expression was also associated with these two sporadic cancers." (PMID 32762026, 2020). "This ability could suggest a mechanism by which an activated FANCA signaling pathway can prevent cancer in cells that do not satisfy the SAC by inducing apoptosis." (PMID 28239445, 2017).
tumor (71 papers, 2005 to 2026). "Immunohistochemistry staining for γH2AX revealed a significantly higher percentage of γH2AX-positive tumor cells in PARPi-treated FANCA-deficient tumors, implicating DNA damage accumulation as a likely driver of tumor cell synthetic lethality." (PMID 40630542, 2025). "The second variant in the same patient c.G1874C (rs139235751) was in the FANCA gene, which is identified as pathogenic in all databases used, was found in the heterozygous state in both tumor and normal tissue that suggests its germinal status." (PMID 36833207, 2023). "The next-generation sequencing analysis results revealed a germline FANCA mutation in the tumor tissue." (PMID 35280757, 2022). "The identification of two patients with tumor predisposition variants (FANCA, NF1) again confirms that the strategy of a broad testing is needed in patients diagnosed with SRS." (PMID 33482836, 2021). "It is further worth noting that NGS-based testing of the tumor sample first, would have also likely identified two heterozygous FANCA mutations." (PMID 31192125, 2019). "In addition to known driver mutations in DNMT3A and IDH1, one patient also had missense tumor specific mutations in the FANCA and FANCM genes." (PMID 36382570, 2023). "Additionally, while candidate PPV/POVs in known GT genes, including BRCA2 (p.Trp31Arg) and FANCA (p.Arg504Gly) showed tumour associated DDR-like mutational signature enrichment, the 28 PPV/POVs in unknown GT-candidates showing DDR-like mutational enrichment provides further merit for consideration." (PMID 41038821, 2025). "The largest tumor volume observed was 0.906 mm3 in the oe-FANCA group, while the vector group showed a smaller tumor volume of 0.312 mm3 4 weeks after the mice were euthanized." (PMID 38682160, 2024). "The main tumor susceptibility genes in CBC3T-1 cells included BARD1, KDR, FAT1, HNF1A, BRCA2, FANCA, and BRCA1." (PMID 37966669, 2024). "Among the rest, one tumor each had a ETV6-NTRK3 fusion, a PTEN deletion, an FGFR1 gain-of-function mutation, a CHEK2 LOF mutation (T367fs*), an AURKA-CSTF1 fusion, and a FANCA deletion." (PMID 38730662, 2024). "Conversely,FANCA overexpression stimulates cell proliferation, migration, and invasion.In vivo xenograft experiments confirm the promotional role of FANCA in GC tumor progression." (PMID 38682160, 2024). "Compared with the vector group, the FANCA overexpression group exhibited a considerable increase in tumor size." (PMID 38682160, 2024). "An upregulation of FANCA expression was observed in the TCGA database when comparing tumor tissues to their corresponding normal tissues." (PMID 38682160, 2024). "There were found pathological mutations in the primary tumour and also in the patient’s lung metastasis samples in the genes BRAF, namely p.V600E (c.1799 T > C), and FANCA, namely p.S858R (c.2574C > G)." (PMID 37573343, 2023). "Two patients had a tumor with a BRCA1 mutation, one had BRCA1 and FANCA mutations, one had a PALB2 mutation, one had a BRCA1 VUS, and one had a BRCA2 VUS." (PMID 37173992, 2023). "The genes BRCA2 (P=0.009),ATM (P=0.004), FANCA (P=0.001), andPARP1 (P=0.011) showed a lower expression in post-NACTresidual tumor samples (n=32) than in pre-NACT biopsy samples (n=98)." (PMID 35293552, 2022). "One tumour showed an alteration in FANCA, one tumour showed an alteration in FANCM (with a concomitant BRCA1 P/LP variant), and one tumour showed an alteration in RAD51C." (PMID 34680387, 2021). "The patient’s formalin-fixed paraffin-embedded tumor biopsy specimen underwent multiple-gene testing by next-generation sequencing, which identified a FANCA homodeletion." (PMID 31931827, 2020). "With regard to tumor suppressors, DSV–iECs showed an equal divide: 2 up-regulated (mutations: DNMT3A; CNAs: FANCA) and 2 down-regulated (CNAs: IRF1, BTG1) genes." (PMID 32934781, 2020). "Because FANCA plays an important role in the repair of DNA damage, it is considered a potential tumor suppressor gene." (PMID 33585230, 2020).